MST1 (macrophage stimulating 1)
Synonyms: MSP; D3F15S2; DNF15S2; HGFL; NF15S2
Target class: Secreted protein
Gene: Protein-coding gene on chromosome 3 (49,683,947 to 49,689,501, reverse strand). Ensembl gene ENSG00000173531.
Subcellular location: Secreted
Subcellular location (Human Protein Atlas): Vesicles; Predicted to be secreted
Pathways (Reactome):
Signal Transduction: Signaling by MST1
Genetic constraint (gnomAD): Loss-of-function variants: 76 observed, 96.75 expected, observed/expected ratio (o/e) 0.79, 90% interval 0.65 to 0.95. The upper end of that interval is the gene's LOEUF score, 0.95, which puts it in group 4 of 6, group 1 being the genes least tolerant of losing a copy. Missense variants: 850 observed, 979.55 expected, observed/expected ratio (o/e) 0.87, 90% interval 0.82 to 0.92. Synonymous variants: 352 observed, 379.82 expected, observed/expected ratio (o/e) 0.93, 90% interval 0.85 to 1.01.
Homologues: Orthologues: chimpanzee MST1 (99% identical), macaque MST1 (96% identical), rabbit MST1 (90% identical), dog MST1 (89% identical), pig MST1 (89% identical), guinea pig MST1 (82% identical), mouse Mst1 (79% identical), rat Mst1 (79% identical), tropical clawed frog mst1 (58% identical), zebrafish mst1 (55% identical), Drosophila melanogaster CG30287 (9% identical), Drosophila melanogaster CG30289 (9% identical), and 9 more. Paralogues in human: HGF (44% identical), HABP2 (18% identical), GZMA (9% identical), GZMK (8% identical), PIK3IP1 (8% identical).
Diseases named in the same sentence as MST1 in open-access papers:
MST1 is named in the same sentence as 251 diseases in open-access papers, as found by Europe PMC text mining. Sharing a sentence is not in itself a finding about the gene and the disease. The quoted sentences say what the papers report.
breast carcinoma (54 papers, 2010 to 2025). "Next, we evaluated the association between endogenous KSR1 and MST1 in MCF-7 breast carcinoma cells." (PMID 41326667, 2025). "MST1 is generally expressed in apoptosis‐promoting kinase, and recently, it is found that inhibition or loss of function of MST1 promotes breast cancer proliferation, as well as protects mouse embryos." (PMID 34318610, 2021). "Another study investigating the mechanism underlying breast cancer cell resistance to MST1/2-dependent apoptosis showed that FGFR4 phosphorylates MST1/2 and inhibits its activation." (PMID 32722184, 2020). "We next asked whether genomic alterations known to drive breast cancer have associations with increased MST1R/MST1 expression." (PMID 35626096, 2022). "Importantly, the relevance of ubiquitin-mediated degradation of the kinases of the pathway is supported by a recent study showing that the E3 ubiquitin ligase RNF6 interacts with MST1 promoting the degradation of this kinase in breast cancer which is associated with short survival." (PMID 36038253, 2022). "XMU-MP-1, an inhibitor of mammalian sterile 20-like protein kinase 1 (MST1) activity, has been shown to reduce the progression of breast cancer in vivo." (PMID 40725144, 2025). "Conversely, an upregulation emerged in genes associated with the inhibition of breast cancer progression, including SIRT2, MST1, and ULK1, indicating the therapeutic potential of the peptide." (PMID 38272230, 2024). "Nilotinib, a serine/threonine kinase mammalian sterile 20-like kinase 1 (MST1) inhibitor, is widely used for adjunctive treatment of early breast cancer." (PMID 37189611, 2023). "Using human breast cancer cell and Mst1 kinase-dead mouse model, we investigated the role of Hippo pathway in mediating chemotherapy-induced cardiomyopathy." (PMID 36632235, 2023). "The anti-cancer effect of DOX was investigated in human breast cancer cells (MDA-MB-231) with the role of Hippo pathway tested by Mst1-knockdown using Mst1-siRNA." (PMID 36632235, 2023). "Because the ERα transcriptional program is essential for the growth of ER+ breast cancer cells, we next examined the effect of MST1/2 inhibition on ERα target gene expression." (PMID 35654829, 2022). "TCGA and METABRIC gene expression and alteration data were used to query the relationships between MST1R and MST1 in breast cancer." (PMID 35626096, 2022). "HDAC6 was shown to decrease the expression of tumor suppressor mammalian STE20-like kinase 1 (MST1) by deacetylating MST1 in breast cancer cells." (PMID 36076996, 2022). "NSUN6 has also been shown to inactivate macrophage stimulating 1 (MST1) and activate yes-associated protein (YAP) target genes in breast cancer through m5C modification, thereby triggering osteoclast differentiation and bone metastasis." (PMID 35562754, 2022). "Consistent with its role in inhibiting YAP, high MST1/2 expression correlates with poor prognosis in ER+ breast cancer patients." (PMID 35654829, 2022). "A significant inverse association between WBP2 and MST1/2 or miR-23a was observed in clinical breast cancer specimens, hence substantiating the relevance of the MST1/2–Dicer–miR-23a–WBP2 axis in breast cancer." (PMID 34831354, 2021). "Consistently, the higher expression of MST1/2 substantially attenuated WBP2-driven breast cancer growth in vivo and in vitro." (PMID 34831354, 2021). "The results showed that co-alterations of the MST1/2-miR-23a-WBP2 corelated with poorer survival in breast cancer patients." (PMID 32820148, 2020). "Recently, FGFR4 has been shown to activate AKT16 and inhibit MST1/217 signaling in breast cancer cells, but the role of FGFR4 in ILC remains uncertain." (PMID 31263748, 2019). "In epithelial breast cancer cells, Scribble facilitates interactions between the core Hippo kinases (MST1/2 and LATS1/2) and TAZ, which acts as a scaffold protein, thereby destabilizing and preventing activation of TAZ." (PMID 30800215, 2019).
breast carcinoma (continued). "Altogether, our results establish a unique oncogenic signaling mechanism—the dominant FGFR4-mediated attenuation of MST1/2-mediated, stress-associated apoptosis in HER2+ breast cancer cells." (PMID 30903103, 2019). "When DNAJB4 was knocked down and then overexpressed in MDA-MB-231 and BT-549 breast cancer cells, Western blot analysis showed that the phosphorylation levels of MST1, LATS1, and YAP were restored, while the total protein expression of MST1, LATS1, and YAP1 remained unchanged." (PMID 37012515, 2023). "Finally, we demonstrate that MST1/2 inhibition can overcome tamoxifen resistance conferred by frequently occurring point mutations in ERα, suggesting that targeting the Hippo pathway could be a potential strategy to overcome endocrine therapy resistance in breast cancer patients." (PMID 35654829, 2022). "Furthermore, the inhibitory effect of XMU-MP-1 on the growth of MCF-7 cells was partially reversed by siRNA-mediated YAP knockdown (KD), suggesting that MST1/2 inhibition blocked ER+ breast cancer cell growth at least in part through YAP." (PMID 35654829, 2022). "Similarly, MST1 has been reported to be downregulated in breast cancer and proposed as a strong prognostic and predictive for disease-free survival." (PMID 32218280, 2020). "Collectively, the in vitro and in silico data support the notion that the MST1/2 → miR-23a → WBP2 could have a clinical significance in breast cancer." (PMID 32820148, 2020). "XMU-MP-1 is able to efficiently inhibit MST1/2 activities in various cell types including hepatocytes, the macrophage cell line, osteosarcoma cell line, rat primary cardiomyocytes, microglial cells, and breast cancer cell lines." (PMID 32987643, 2020). "Nevertheless, current results show that active FGFR4 tyrosine phosphorylates and inactivates the pro-apoptotic MST1/2 serine/threonine kinase in breast cancer cells, thus revealing a novel mechanism of RTK-mediated apoptosis evasion and oncogenic FGFR4 function." (PMID 30903103, 2019). "As FGFR4 is suitable for targeting, these results raise tempting questions, whether FGFR4 inhibition in HER2+ breast cancer would release the intrinsic MST1/2-mediated apoptotic machinery." (PMID 30903103, 2019). "Although we have demonstrated that pharmacological inhibition of MST1/2 can impede ER+ breast cancer growth in vivo, the subcutaneous xenograft model employed in our study requires supraphysiological concentrations of estrogen and thus may compromise clinical relevance." (PMID 35654829, 2022). "Indeed, daily injection of XMU-MP-1 in estrogen-supplemented female NOD scid gamma (NSG) mice bearing MCF-7 xenografts over a 3-week period significantly inhibited tumor growth compared with vehicle treatment, suggesting that MST1/2 inhibition can reduce ER+ breast cancer growth in vivo." (PMID 35654829, 2022). "Interestingly, one case showed nuclear MST1 expression, which may reflect apoptosis-related signaling, as such translocation has been linked to caspase-mediated cleavage in pancreatic and HER2-positive breast cancer." (PMID 40649713, 2025). "In breast cancer, ROR1–HER3 signaling inactivates Hippo/MST1 through lncRNA‐mediated methylation, which activates YAP and promotes bone metastasis." (PMID 40895190, 2025). "We observed in MDA-MB-231 breast cancer cells that DOX-induced cell death and viability decrease are accompanied with and also indispensable to Mst1 activation/YAP inactivation, suggesting that withdrawal of transcriptional activity of YAP is a key mechanism." (PMID 36632235, 2023). "Methods and Results: In human breast cancer cells, doxorubicin (DOX) significantly induced upregulation of Hippo kinase Mst1, inhibitory phosphorylation of YAP, mitochondrial damage, reduced cell viability and increased apoptosis." (PMID 36632235, 2023).
breast carcinoma (continued). "We showed in breast cancer cells that DOX-induced cell apoptosis and mitochondrial damage were markedly attenuated by Hippo pathway inactivation through Mst1 gene silencing, but simulated by verteporfin through inhibiting YAP transcriptional activity." (PMID 36632235, 2023). "We find that inhibition of Hippo/MST1/2 or activation of YAP blocks the ERα transcriptional program and ER+ breast cancer growth." (PMID 35654829, 2022). "Here we report a case of robust glycemia and HbA1c normalization in a patient with breast cancer-T2D comorbidity under neratinib, a potent triple kinase inhibitor of HER2/EGFR and MST1." (PMID 35370966, 2022). "We find that pharmacological inhibition of the MST1/2 kinase activity, as well as ectopic activation of YAP, inhibits ERα transcription program and ER+ breast cancer growth." (PMID 35654829, 2022). "In gynecological and breast cancers, we found overexpressed PRKACB in BRCA (22%, FDR = 3.7E − 5), MST1 in UCEC (21%, FDR = 1E − 4), and CALM1 in OV (19%, FDR = 1.3E − 3)." (PMID 34552204, 2021). "Next, we analyzed the protein expression of MST1, MST2, and WBP2 in a panel of breast cancer cell lines to determine the correlation between MST and WBP2 expression." (PMID 32820148, 2020). "The main Hippo components are differentially expressed across cancer types, such as in the cases of MST1/2 in soft tissue sarcomas, LATS1/2 in astrocytoma and breast cancers, TAZ in breast cancer, and MOB1 in lung and colon cancers." (PMID 32722184, 2020). "To address this question, we probed the METABRIC and TCGA datasets on cBioportal for MST1 and MST1R mRNA expression using the PAM50 breast cancer subsets to divide the samples." (PMID 32484599, 2020). "Vitamin E analogues activate MST1 and ERK signaling in T-ALL cells and breast cancer cells leading to apoptosis induction." (PMID 32375238, 2020). "Previous studies have shown that MST1 mRNA and RON protein are increased in human ductal breast carcinoma tissue when compared to normal breast tissue." (PMID 32484599, 2020). "The combination of PI3K/mTOR inhibitors with FGFR4 inhibitor BLU9931 potentiates MST1 activation and induces apoptosis in HER2+ breast cancer cells." (PMID 32375238, 2020). "Breast cancer cells co-expressing MST1-K59R and WBP2 significantly decreased the overall survival of the animals compared to those expressing MST1-K59R alone supporting WBP2 and MST as prognostic factors." (PMID 32820148, 2020). "The Mst1-JNK axis is known to control mitochondrial fission in liver cancer, hyperglycemia-induced vascular dysfunction, thyroid carcinoma, breast cancer, acute cardiac stress, and colorectal cancer." (PMID 31631063, 2019). "Although YAP (pS127 and total) was decreased in FGFR4-overexpressing breast cancers (TCGA RPPA), the FGFR4-dependent and -independent modulation of MST1/2 had variable effects on YAP S127 phosphorylation or localization." (PMID 30903103, 2019). "Blockade of this phosphorylation by Y433F mutation induced MST1 activation, as indicated by increased threonine phosphorylation of MST1/2, and the downstream substrate MOB1, in FGFR4-overexpressing T47D and MDA-MB-231 breast cancer cells." (PMID 30903103, 2019). "Importantly, the specific knockdown or short-term inhibition of FGFR4 in endogenous models of human HER2+ breast cancer cells likewise led to increased MST1/2 activation, in conjunction with enhanced MST1 nuclear localization and generation of N-terminal cleaved and autophosphorylated MST1." (PMID 30903103, 2019). "In this study, we demonstrate neratinib as the inhibitor of MST1, a previously unappreciated activity alongside the dual inhibition of HER2/EGFR that drives its clinical utility in breast cancer." (PMID 31676778, 2019). "Here, we show that in FGFR4+/HER2+ breast cancer cells, particularly under tumor-mimicking 3D conditions, FGFR4 depletion-induced MST1/2 autophosphorylation coupled with MST1 cleavage and nuclear localization without additional stimuli." (PMID 30903103, 2019).
breast carcinoma (continued). "Unexpectedly, MST2 was also essential for this MST1/N activation and coincident apoptosis induction, although these two kinases, as well as YAP, were differentially regulated in the breast cancer models analyzed." (PMID 30903103, 2019). "In breast cancer, a recent work revealed that while LATS1/2 and MST1/2 reduce the expression of the immune checkpoint molecule PD-L1 in cancer cells, YAP/TAZ have an opposite effect." (PMID 30619734, 2018). "This leads to methylation and inactivation of MST1, which liberates YAP and increases breast cancer cell metastasis to the bone." (PMID 30619734, 2018). "We found that in breast cancer cells, overexpression of RASSF1A enhanced MST1/2 phosphorylation as expected, but RASSF1C overexpression slightly reduced it." (PMID 24327924, 2013). "In breast cancer, lncRNA AATBC functions as a Y-box binding protein 1 (YBX1) scaffold and controls Hippo signaling through lncRNA AATBC/YBX1/mammalian sterile 20 like kinase 1 (MST1) axis." (PMID 39313797, 2024). "In breast cancer, a recently identified lncRNA known as MAYA can act as an adaptor, recruiting LLGL and NSUN6 to facilitate MST1 inactivation by directly mediating the methylation of MST1 at Lys59." (PMID 38067201, 2023). "In breast cancer, the ROR1-HER3 pathway recruited the lncRNA MAYA and the methyltransferase NSUN6, driving MST1 methylation and consequently reducing MST1 kinase activity." (PMID 37927473, 2023). "A significant positive correlation of MST1R and MST1 with M2 macrophage infiltration and naïve T cell responses was identified by examining the tumor immune microenvironment estimation resource (TIMER) from breast cancer data from TCGA with MST1R and MST1 expression." (PMID 35626096, 2022). "In breast cancer cells, NSUN6 can form a complex with the proteins LLGL2 and lncRNA Maya, which inactivates the kinase Hippo/MST1 through methylation of Hippo/MST1, resulting in promotion of tumor metastasis." (PMID 34630524, 2021). "Given the lack of consistency in expression differences between PAM50 subsets in the METABRIC and TCGA datasets and the lack of difference between histological subgroups, these data indicate that MST1 and MST1R expression is mostly uniform across human breast cancer subtypes." (PMID 32484599, 2020). "Our analysis of drug‐resistant breast cancer cells indicated that MET increased SCRIB expression, which then recruited MST1/2 and LATS1 to the plasma membrane, leading to YAP phosphorylation and its retention within the cytoplasm, and finally to inhibition of cell proliferation and invasion." (PMID 32281270, 2020). "However, our experiments on MCF-7 human breast cancer cells treated with DOX and XMU-MP-1, a novel MST1 pharmacological inhibitor, showed that MST1 inhibition does not only affect DOX cytotoxicity at all, but it reduces the clonogenic potential of cancer cells, also in the absence of DOX treatment." (PMID 37566283, 2023). "To determine whether MST1/2 inhibition could inhibit the hormonal therapy-resistant ERα mutant in vivo, we generated ERα-Y537S-expressing MCF-7 xenografts as well as patient-derived xenograft (PDX) models bearing WHIM20 breast cancer cells." (PMID 35654829, 2022). "To determine whether increasing YAP activity can inhibit the growth of ER+ breast cancer cells, we took advantage of a pharmacological small molecule inhibitor, XMU-MP-1, which specifically inhibits the kinase activity of MST1/2, thereby promoting YAP nuclear localization and activation." (PMID 35654829, 2022). "We plated MCF-7 breast cancer cells and then treated them with DOX for four hours, with or without XMU-MP-1, a novel MST1 pharmacological inhibitor." (PMID 37566283, 2023).